USP10 (ubiquitin specific peptidase 10)
Diseases named in the same sentence as USP10 in open-access papers (continued):
Sharing a sentence is not in itself a finding about the gene and the disease.
Alzheimer disease (5 papers, 2020 to 2025). A progressive, neurodegenerative disease characterized by loss of function and death of nerve cells in several areas of the brain leading to loss of cognitive function such as memory and language. "For example, USP10 stabilizes tau protein, leading to neurofibrillary tangles and neuronal toxicity in Alzheimer's disease (AD)." (PMID 40785597, 2025). "However, Spautin-1 cannot effectively cross the blood-brain barrier, which poses a major challenge for inhibiting USP10 in the treatment of Alzheimer’s disease (AD)." (PMID 39562545, 2024).
ischemic stroke (5 papers, 2023 to 2026). A stroke disorder caused by obstruction of blood flow to the brain, due to thrombotic (local blood clot formation) or embolic (due to a blood clot or other material traveling from another site) event. "Our results revealed that the VNS-induced enhancement of USP10 was a mechanism to attenuate neurological dysfunction, neuroinflammation, and glial cell activation caused by ischaemic stroke, and this effect was achieved by the modulation of the NF-κB signaling pathway." (PMID 37153558, 2023). "However, the studies related to the regulation of USP10 after ischemic stroke are limited, and the specific mechanisms underlying how USP10 exerts its role in ischemic stroke need to be elucidated." (PMID 37153558, 2023). "By directly interacting with Transforming Growth Factor β-Activated Kinase 1 (TAK1), USP10 protects against cerebral I/R injury after ischemic stroke." (PMID 39649720, 2024). "Collectively, TSG facilitated PINK1/Parkin pathway-mediated mitophagy by upregulating USP10/YBX1 axis to ameliorate ischemic stroke." (PMID 39406480, 2024). "Taken together, these evidences suggest that increasing USP10 expression in the brain is a preventative strategy for ischaemic stroke-induced neuroinflammation response and subsequent brain damage." (PMID 37153558, 2023). "Our results implied that the VNS-induced increase in USP10 level is associated with the deubiquitination of NEMO and finally the inhibition of NF-κB signaling pathway in ischaemic stroke." (PMID 37153558, 2023). "We hypothesized that TSG upregulated USP10 to improve brain injury in ischemic stroke via promoting PINK1/Parkin-mediated mitophagy." (PMID 39406480, 2024). "Therefore, in order to explore whether USP10 is the potential mediator for VNS to alleviate neuroinflammation in ischaemic stroke, we chose 72h post-tMCAO as the time point for the follow-up experiments." (PMID 37153558, 2023). "Therefore, this study investigated whether USP10 plays a key role in the protective effect of VNS against ischemic stroke and explore its mechanism." (PMID 37153558, 2023). "Therefore, in order to explore whether USP10 is the potential mediator for vagus nerve stimulation to alleviate neuroinflammation in ischaemic stroke, we chose 72h as the time point for the follow-up experiments." (PMID 37153558, 2023). "Mechanically, TSG upregulated USP10 to elevate YBX1 protein expression, thereby facilitating PINK1/Parkin-mediated mitophagy and improving ischemic stroke injury." (PMID 39406480, 2024). "The present study showed that the upregulation of USP10 exerted by VNS treatment was most significant at 72h, a time point that is considered an important time frame for ischaemic stroke therapies." (PMID 37153558, 2023). "USP10 is a potential mediator for VNS to alleviate neurological deficits, neuroinflammation, and glial cell activation in ischaemic stroke by inhibiting NF-κB signalling pathway." (PMID 37153558, 2023). "Our results revealed that enhanced USP10 was required for VNS to attenuate neurological deficits, neuroinflammation, and glial cell activation in ischaemic stroke by regulating NF-κB signaling pathway." (PMID 37153558, 2023). "However, this protective role of VNS was suppressed by USP10 silencing, which further indicated that USP10 plays a critical role in the anti-neuroinflammation effect of VNS against ischaemic stroke." (PMID 37153558, 2023). "Our study found that USP10 expression in the brain was decreased after ischaemic stroke, and VNS treatment could counteract it by promoting USP10 expression." (PMID 37153558, 2023). "Our results demonstrated a gradual decrease of USP10 level following ischaemic stroke, while this level was upregulated by VNS treatment resulting in reduced cerebral infarct volume and alleviated neurological deficits; however, this protective effect was blocked by USP10 silencing." (PMID 37153558, 2023).
osteosarcoma (5 papers, 2021 to 2026). A usually aggressive malignant bone-forming mesenchymal neoplasm, predominantly affecting adolescents and young adults. "Our study also showed that USP10 is associated with disease progression and poor prognosis in osteosarcoma patients." (PMID 37184153, 2023). "Association of USP10 expression with clinical features in osteosarcoma patients." (PMID 37184153, 2023). "As for metabolic reprogramming, SPICE1 facilitates osteosarcoma progression by enhancing USP10-mediated deubiquitination and stabilization of FASN, thereby fueling lipid biosynthesis and tumor growth." (PMID 41522354, 2026). "In this study, we investigated the clinical and pathological significance of USP10 and Unc-51-like autophagy activating kinase 1 (ULK1) in osteosarcoma (OS), as well as the mechanism of USP10 action in ULK1-mediated autophagy and disease progression." (PMID 39218913, 2024). "Next, to further study whether USP10 affects YAP1 protein degradation, we knockdown or overexpression of USP10 in osteosarcoma cells and examined the impact of various expression patterns of USP10 on YAP1 protein levels in cells treated with or without MG132." (PMID 37184153, 2023). "In summary, USP10 positively regulates YAP1 protein expression in osteosarcoma cells." (PMID 37184153, 2023). "This research aimed to elucidate the roles of USP10 and YAP1 in osteosarcoma EMT as well as distant metastasis." (PMID 37184153, 2023). "Simultaneously, we also observed that USP10 could affect the EMT and osteosarcoma cells' invasiveness and migration in vivo and in vitro." (PMID 37184153, 2023). "We further investigated the mechanisms of USP10 and YAP1 in osteosarcoma EMT, confirming that USP10 regulates YAP1 expression through altering the breakdown and ubiquitination of the downstream gene YAP1, thereby affecting the EMT and distant metastasis of osteosarcoma." (PMID 37184153, 2023).
cardiac hypertrophy (4 papers, 2021 to 2024). "Additionally, a study reported of important roles of Sirt6 in regulating in cardiac hypertrophy associated with deubiquitinase ubiquitin-specific protease 10 (USP10)." (PMID 37497437, 2023). "The USP10 attenuates aortic constriction-induced cardiac hypertrophy by directly regulating Sirt6 levels (Zhang DH." (PMID 37497437, 2023). "Additionally, USP10 functions as a Sirt6 deubiquitinase to promote tumorigenesis and cardiac myocyte hypertrophy." (PMID 39430239, 2024). "Inhibition of USP10 exacerbated cardiac hypertrophy by regulating sirtuin 6 (Sirt6) signaling." (PMID 34957094, 2021). "Studies have found that USP10 acts as a deubiquitinase of Sirt6 to induce cardiomyocyte hypertrophy and trigger cardiac hypertrophy, and cardiac fibroblasts could aggravate myocardial ischemia–reperfusion fibrosis by enhancing USP10‐dependent Smad4 deubiquitination." (PMID 39517125, 2024).
head and neck squamous cell carcinoma (4 papers, 2022 to 2025). A squamous cell carcinoma that arises from any of the following anatomic sites: lip and oral cavity, nasal cavity, paranasal sinuses, pharynx, larynx, and salivary glands. "In contrast, USP10 upregulation was associated with poor prognosis in head and neck squamous cell carcinoma (HNSC)." (PMID 36248971, 2022). "Here, it is discovered that USP10 as a member of DUBs, is tightly associated with a poor prognosis in patients with head and neck squamous cell carcinoma (HNSCC)." (PMID 40605431, 2025). "This study identifies USP10 as a novel deubiquitinase that antagonizes ferroptosis in head and neck squamous cell carcinoma (HNSCC)." (PMID 40605431, 2025).
amyotrophic lateral sclerosis (3 papers, 2024 to 2025). Amyotrophic lateral sclerosis (ALS) is a neurodegenerative disease characterized by progressive muscular paralysis reflecting degeneration of motor neurons in the primary motor cortex, corticospinal tracts, brainstem and spinal cord. "In amyotrophic lateral sclerosis (ALS) and frontotemporal dementia (FTD), USP10 dysfunction hinders autophagy, causing misfolded protein accumulation in motor neurons." (PMID 40785597, 2025). "Therefore, investigating the role of USP10-regulated CMA in protein aggregation and pathogenesis of AD and amyotrophic lateral sclerosis could provide valuable insights." (PMID 40419127, 2025).
atherosclerosis (3 papers, 2020 to 2022). A disease characterized by the build-up of fatty material and calcium deposition in the arterial wall resulting in partial or complete occlusion of the arterial lumen. "In conclusion, USP10 promotes the development and progression of atherosclerosis through stabilizing CD36 protein expression." (PMID 33197885, 2020). "USP10 can interact with CD36 by removing the polyubiquitin on CD36 to stabilize the CD36 protein, thereby promoting foam cell formation and lipid accumulation and promoting the development of atherosclerosis, whereas inhibition or knockdown of USP10 can have the opposite effect." (PMID 36611964, 2022). "But the pathophysiology of USP10 in atherosclerosis has not been validated." (PMID 33197885, 2020).
cervical cancer (3 papers, 2022 to 2023). A primary or metastatic malignant neoplasm involving the cervix. "SGs have also been shown to inhibit cervical cancer cell apoptosis by inhibiting ROS production, which may be mediated by the activation of ubiquitin-specific peptidase 10 (USP10)." (PMID 37179344, 2023).
cystic fibrosis (3 papers, 2018 to 2020). Autosomal recessive disorder caused by pathogenic variants in the CFTR gene (cystic fibrosis transmembrane conductance regulator), which encodes a chloride and bicarbonate channel expressed in epithelial cells, and follow the diagnosis criteria. "We tested the effect of spautin-1 on F508del-CFTR since it is an inhibitor of USP10 deubiquitinase and of autophagy, a target and a biological process that have been associated with cystic fibrosis and mutant CFTR." (PMID 30618756, 2018). "The role of USP10 is not only relevant in cancer but it also has prominent roles in neurodegenerative disease, cystic fibrosis, and some infectious disease." (PMID 33277473, 2020). "Therefore, USP10 expression may be advantageous in cystic fibrosis patients to promote CFTR recycling to the epithelial surface." (PMID 33277473, 2020). "Expression of USP10 in human airway epithelial cells is therefore protective for CFTR abundance and chloride secretion, which is beneficial to patients with pneumonia, chronic obstructive pulmonary disease (COPD), and cystic fibrosis." (PMID 33277473, 2020). "Additionally, a better understanding of the role of USP10 in the endocytic trafficking of CFTR and other ion channels has the potential to identify new targets for drug development in multiple diseases, including cystic fibrosis." (PMID 33277473, 2020).
endometriosis (3 papers, 2020 to 2024). The growth of functional endometrial tissue in anatomic sites outside the uterine body. "For example, USP10 promotes proliferation and migration and inhibits apoptosis of endometrial stromal cells in endometriosis by activating the Raf-1/MEK/ERK pathway." (PMID 33133065, 2020).
leukemia (3 papers, 2021 to 2024). A malignant (clonal) hematologic disorder, involving hematopoietic stem cells and characterized by the presence of primitive or atypical myeloid or lymphoid cells in the bone marrow and the blood. "USP10 inhibition by HBX19818 shows anti-leukemia effect in FLT3-ITD positive AML cells and mouse models." (PMID 34454635, 2021). "Also, other deubiquitinases, such as USP2, USP8, USP10 and USP42, fuse with leukemia-associated genes, indicating that deubiquitinases play an important role in the pathogenesis of AML." (PMID 34454635, 2021). "USP10 can deubiquitinate and stabilize YAP1, and its inhibitor Wu-5 was found to potently suppress leukemia, exhibiting its potential for eliminating undruggable oncoproteins to restore immunosurveillance." (PMID 38715050, 2024). "Another USP10 inhibitor, Wu-5, also shows anti-AML effect and overcomes FLT3 inhibitor resistance and synergistically enhances the anti-leukemia effect of crenolanib through targeting both FLT3 and AMPKα pathway." (PMID 34454635, 2021). "Spleen tyrosine kinase (SYK), stabilized by USP10, is critical for AML transformation and maintenance of the leukemia clone in AML patients." (PMID 34454635, 2021). "Until now, USP2, USP8, and USP10 have been found to be fused with MLL, which indicates that DUBs may be potential targets of MLL-r leukemia." (PMID 34454635, 2021).
lung adenocarcinoma (3 papers, 2020 to 2023). A carcinoma that arises from the lung and is characterized by the presence of malignant glandular epithelial cells. "Loss of USP10 downregulates KLF4 expression and accelerates KRASG12D-driven initiation and progression of lung adenocarcinoma." (PMID 36969062, 2023).
lymph node metastasis (3 papers, 2022 to 2024). "We also expanded the research samples to explore the clinical relevance, finding that high USP10 expression levels are often associated with lymph node metastasis." (PMID 39430239, 2024). "Further studies showed that high USP10 expression correlated closely with the stage of cancer and the presence of lymph node metastasis in patients suffering from various types of cancer." (PMID 35433424, 2022). "For lymph node metastasis, patients with LUSC, READ, and LUAD with N0, N1, or N2 metastasis, USP10 expression was higher than that in patients with other stages of metastasis." (PMID 35433424, 2022).
Myocardial fibrosis (3 papers, 2021 to 2026). "Conversely, USP10 inhibition significantly offset the cardioprotective effect of FSTL1 by increasing myocardial fibrosis." (PMID 34957094, 2021). "The present study employed both in vivo and in vitro experiments to decipher the changes in Notch1 and USP10 and to evaluate the possible interaction between FSTL1 and USP10 in the pathological mechanism of MI-induced myocardial fibrosis in T2DM." (PMID 34957094, 2021). "Our in vivo study revealed that intracardiac delivery of AAV9-FSTL1 alleviated cardiac dysfunction by activating USP10 and alleviating myocardial fibrosis." (PMID 34957094, 2021). "Further in vitro analysis provided evidence that FSTL1 activated USP10/Notch1 signaling to inhibit myocardial fibrosis." (PMID 34957094, 2021). "The present study revealed that FSTL1 and USP10 were significantly activated in T2DM mice with MI, and FSTL1 treatment further increased USP10 activation and alleviating cardiac dysfunction by reducing myocardial fibrosis." (PMID 34957094, 2021). "In conclusion, FSTL1 treatment ameliorated cardiac dysfunction in MI with co-existent T2DM, possibly through inhibition of myocardial fibrosis and apoptosis by upregulating USP10/Notch1 signaling." (PMID 34957094, 2021). "Our present study revealed that FSTL1 protected cardiac function against MI-induced myocardial fibrosis in T2DM through a USP10/Notch1-dependent mechanism." (PMID 34957094, 2021). "In addition, in specific models of “MI plus type 2 diabetes,” exogenous supplementation or overexpression of FSTL1 reduced myocardial fibrosis and improved cardiac function through the USP10/Notch1 axis." (PMID 41602834, 2026). "In addition, myocardial fibrosis in perivascular and interstitial spaces were significantly increased in USP10-CKO mice." (PMID 34957094, 2021). "Moreover, our results establish a crosstalk between USP10 and Notch1 in the inhibition of myocardial fibrosis and improvement in cardiac function by alleviating adverse remodeling against MI injury in T2DM and may provide better prognosis for T2DM patients with MI." (PMID 34957094, 2021).
pancreatic ductal adenocarcinoma (3 papers, 2022 to 2025). An infiltrating adenocarcinoma that arises from the epithelial cells of the pancreas. "Our protein and RNA level analysis from archived specimens and public databases show that USP10 is overexpressed in pancreatic ductal adenocarcinoma (PDAC) and expression correlates with poor overall patient survival." (PMID 36543867, 2022). "However, the relationship between USP10 and pancreatic ductal adenocarcinoma (PDAC) is poorly understood." (PMID 39430239, 2024).
Pancytopenia (3 papers, 2016 to 2023). An abnormal reduction in numbers of all blood cell types (red blood cells, white blood cells, and platelets). "USP10 is crucial for hematopoiesis; in a study in mice, all USP10 knockout mice died within 1 year due to bone marrow failure with pancytopenia i.e., deficiency of all three cellular components—red cells, white cells, and platelets." (PMID 33277473, 2020). "This BM failure with pancytopenia in USP10-KO mice was caused by the prominent reduction of hematopoietic stem/progenitor cells (HSPCs), especially long-term HSCs (LT-HSCs)." (PMID 27974222, 2016). "In this study, we found that systemic USP10-KO mice develop BM failure with pancytopenia including severe anemia, which is caused by the severe reduction of LT-HSCs (CD150+CD48− LSK) in FL and BM." (PMID 27974222, 2016). "Further, USP10’s importance for life is underlined by the fact that USP10 knockout mice died within 1 year due to bone marrow failure with pancytopenia suggesting that USP10 controls differentiation, and apoptosis which are also crucially linked to tumorigenesis." (PMID 37371055, 2023). "All USP10 knockout (KO) mice died within 1 year because of bone marrow failure with pancytopenia." (PMID 27974222, 2016). "Collectively, these results suggest a potential intrinsic defect in USP10-KO HSCs, which could cause the reduction of HSC numbers and the development of BM failure with pancytopenia." (PMID 27974222, 2016).
small intestinal adenocarcinoma (3 papers, 2020 to 2022). "In patients with small intestinal adenocarcinoma, loss of USP10 and p14ARF is associated with poor prognosis." (PMID 33277473, 2020). "In 195 surgically resected small intestinal adenocarcinoma tumors, USP10 expression was significantly decreased compared to normal tissue." (PMID 33277473, 2020).
steatosis (3 papers, 2023 to 2025). Increased lipid within the cytoplasm of cells. "Interestingly, the USP10 and C/EBPβ protein levels were increased in the livers of spautin-1–treated HFD mice, which is opposite to the pattern observed in the adipose tissue but consistent with reports linking hepatic USP10 upregulation with steatosis improvement." (PMID 41417444, 2025).
viral infection (3 papers, 2020 to 2024). "Takahashi and colleagues discovered that USP10 acts as an anti-stress factor in response to various environmental stressors, including viral infections and oxidative stress." (PMID 39048945, 2024). "USP10, a member of the ubiquitin-specific protease family of cysteine proteases, has been demonstrated to serve as an anti-stress factor under a variety of stressful circumstances, including oxidative stress, thermal shock, and viral infection." (PMID 37153558, 2023).
acute kidney injury (2 papers, 2021 to 2025). Sudden and sustained deterioration of the kidney function characterized by decreased glomerular filtration rate, increased serum creatinine or oliguria. "Recent research reports USP10 deubiquitinating regulates FOXQ1, which plays a protective role in sepsis-induced acute kidney injury (S-AKI) by inducing inflammation and apoptosis." (PMID 41347087, 2025).
bladder cancer (2 papers, 2011 to 2022). "Second, in U2OS bladder cancer cells, the interaction between G3BP1 and USP10 inactivates the deubiquitinating enzyme activity of USP10." (PMID 21455491, 2011).